TF (transferrin)
Diseases named in the same sentence as TF in open-access papers (continued):
Sharing a sentence is not in itself a finding about the gene and the disease.
COVID-19 (continued). "Using only 2 reference genes, we were able to isolate 12 shared TFs and 25 shared TF-miRNAs.by FFL tool, This FFL among CCL20, miR-1256 and PPARG may be a novel regulatory module in COVID-19 complicated with pulmonary hypertension." (PMID 38653779, 2024). "None of transferrin isoforms changed in COVID-19 patients depending on the modifited early warning score (MEWS) (p = 0.327, p = 0.110, p = 0.064 and p = 0.544, respectively, for 5-sialoTRF, 4-sialoTRF, 3-sialoTRF and 2-sialoTRF)." (PMID 38673719, 2024). "COVID-19 patients with hypoxia appear to be suffering from prothrombotic conditions, through the upregulation of PAI-1 and the stimulation of procoagulants synthesis, like TF and von Willebrand Factor (vWF)." (PMID 36295093, 2022). "Of note, decreased transferrin in COVID-19-positive patients was not related to a hepatic disorder, as 91.5% of the patients with low transferrin levels had alanine aminotransferase concentration below twice the highest normal value." (PMID 34960751, 2021). "Finally, a total of eleven differential factors related to COVID-19 disease severity were identified, including: TRAIL R1, IGFBP-1, IGFBP-4, VCAM-1, sFRP-3, FABP2, Transferrin, GDF15, IL-1F7 (also known as IL-37), IL-5Rα, and CD200." (PMID 34335566, 2021). "Accordingly, transferrin level was also lower in COVID-19-positive compared to COVID-19-negative patients." (PMID 34960751, 2021). "Serum iron and transferrin levels at admission were lower in COVID-19-positive than in COVID-19-negative patients." (PMID 34960751, 2021). "Decreased transferrin and transferrin saturation were found in COVID-19 patients in 3 previous studies, but not in another one." (PMID 34960751, 2021). "In the correlation analysis, the serum 25(OH)D concentration of SARS-CoV-2 positive patients was not related to any parameter used as a biomarker in COVID-19, such as transferrin, ferritin, and D-dimer (data not shown)." (PMID 34299717, 2021). "It is not yet clear whether IV infusion is a safe and effective route of MSC delivery in COVID-19, since MSC-based products express variable levels of highly procoagulant tissue factor (TF/CD142), compromising the cells' hemocompatibility and safety profile." (PMID 32574263, 2020). "COVID-19 patients with severe disease exhibit increased monocyte counts with higher frequencies of classical monocytes, lower frequencies of intermediate/non-classical monocytes and elevated plasma levels of C-reactive protein (CRP) and serum TF in comparison to mild disease." (PMID 38555403, 2024). "Considering poor classification performance for both severe illness and hospitalization and only fair performance for survival based on our analysis, transferrin is not a reliable marker to use in everyday practice for ambulatory care COVID-19 patients assessment compared to other APRs investigated." (PMID 37790210, 2023). "Traditionally, CRP has been used as a systemic clinical marker of inflammation in COVID-19 and other diseases, although the SROC curves suggest that other acute phase proteins, such as ORM1, CRTAC1, SERPINA3, TF, and AHSG might perform better as biomarkers of inflammation." (PMID 37739942, 2023). "Iron parameters, such as ferritin and transferrin, are not yet considered standard biomarkers for monitoring COVID-19 disease progression because the relationship between iron metabolism and COVID-19 remains unclear." (PMID 35204599, 2022). "COVID-19 can lead to a form of disseminated intravascular coagulation (DIC) and many of the critically ill COVID-19 patients with poor prognosis are in a systemic procoagulant state, and MSC products are known to express variable levels of a highly procoagulant tissue factor (TF/CD142)." (PMID 33520970, 2020).
COVID-19 (continued). "Furthermore, TF activation has been reported in the presence of SARS-CoV-2, and there is evidence that TF expression can be disrupted by inhibiting the complement component C3, suggesting that the complement axis plays a critical role in COVID-19-induced inflammation." (PMID 38933264, 2024). "However, (SARS-CoV-2-induced) locally produced transferrin may contribute to COVID-19 pathology, even independent of circulating transferrin levels." (PMID 32751741, 2020). "In another study involving COVID-19 patients in ICU, transferrin levels showed non-significant subtle alterations (both increment and decrement) through the period of 18 days in ICU, with subtly higher levels on days 15–18 compared to days 1–2 of the ICU stay." (PMID 35849261, 2023). "Thus, MSCs which are going to be used for COVID-19 should express only low levels of TF/CD142, since the molecule by itself may initiate the clotting process, and also because MSCs from different sources have been reported to express varying degrees of TF/CD142." (PMID 33102489, 2020).
glioma (79 papers, 2011 to 2025). A benign or malignant brain and spinal cord tumor that arises from glial cells (astrocytes, oligodendrocytes, ependymal cells). "Using tetrahydrocurcumin and doxorubicin-loaded transferrin-conjugated nanoparticles caused a significantly larger cytotoxic effect than treatment with doxorubicin-loaded nanoparticles alone in glioma cells." (PMID 32486019, 2020). "Overexpression of EGFR in A431 human carcinoma cells and glioma cells causes increased TF expression which functions in tumor initiation and angiogenesis." (PMID 24086497, 2013). "Our DRA-based three-TF signature genes have been proved to be more causal and help to generate testable hypothesis on glioma carcinogenesis." (PMID 27586240, 2016). "Next, using Annexin V-FITC/PI dual staining, we evaluated the effects of different concentrations of Cur, Cur-Nio, and TF-Cur-Nio on the apoptosis of C6 glioma cells." (PMID 40140588, 2025). "The resulting TF-modified curcumin niosomes (TF-Cur-Nio) demonstrated enhanced targeting of brain tumors, improved anti-glioma efficacy, and favorable in vivo safety." (PMID 40140588, 2025). "For example, transferrin strongly influences the binding of magnetic PLGA particles to glioma cells, and the results of in vivo experiments revealed that particles with transferrin loaded with doxorubicin and paclitaxel significantly suppress tumor growth." (PMID 40076706, 2025). "This study designed and prepared TF-Cur-Nio for targeted therapy against glioma, effectively enhancing the brain tumor-targeting ability and anti-glioma efficacy of Cur." (PMID 40140588, 2025). "The TF-Cur-Nio group presented an increased nuclear-to-cytoplasmic ratio, with mostly oval or nearly oval nuclei, fewer glioma cells, more abundant cytoplasm, and greater differentiation." (PMID 40140588, 2025). "Based on the successful establishment of the in-situ C6 glioma nude mouse model, we proceeded to evaluate the pharmacodynamic effects of Cur-Nio and TF-Cur-Nio in vivo." (PMID 40140588, 2025). "In contrast, the TF-Cur-Nio group exhibited a marked increase in the number of apoptotic glioma cells, highlighting its strong ability to induce apoptosis." (PMID 40140588, 2025). "Currently, several surface receptors distinct from those found in other normal tissues, such as transferrin (TF), lipoprotein, or insulin-like growth factor receptors have been identified on the surfaces of brain capillary endothelial cells and glioma cells." (PMID 40140588, 2025). "Using SCENIC 45, 46, we computed transcription factor regulons (TF-regulons) from single-cell sequencing data, effectively distinguishing the 13 glioma subclusters through binary regulon activity." (PMID 38994023, 2024). "TF expression was demonstrated to predict a poor prognosis in breast cancer and to correlate with the grade of malignancy in glioma and pancreatic cancer." (PMID 36980251, 2023). "Used approaches unambiguously demonstrated that transferrin-conjugated encapsulins were captured by glioma cells much more efficiently than by benign cells." (PMID 37896182, 2023). "Accordingly, Sun and co-workers showed the regulation of TF expression by the miR200a/ZEB1 axis in glioma cells." (PMID 38201433, 2023). "Our experience with glioma-targeted liposomal NP delivery of cytotoxic therapies across the BBB in mouse models of glioma has demonstrated successful accumulation of transferrin-functionalized NPs on the surface of glioma tumors." (PMID 35223783, 2022). "It was also suggested that glioma-derived podoplanin and TF coexpressing EVs cooperatively enhance micro-thrombosis in glioma xenograft murine models." (PMID 36013171, 2022).
glioma (continued). "We further demonstrated that Sev treatment suppressed the expression of GPX4, while upregulating the expression of transferrin and ferritin and Beclin-1 in glioma cells in a dose-dependent manner." (PMID 35372041, 2022). "Research reported that dual targeting DOX liposomes conjugated with TF and folate yielded anti-cancer effects in C6 glioma cells." (PMID 34575511, 2021). "It has been shown that transferrin-functionalised porous silicon nanoparticles (Tf@pSiNPs) can inhibit the migration of U87 glioma cells." (PMID 33637089, 2021). "Transferrin functionalisation has been found to increase the rate and extent of nanoparticle-uptake by glioma cells, and to allow traversing across in vitro models of the blood brain barrier (BBB)." (PMID 33637089, 2021). "Pretreatment with tetrahydrocurcumin and doxorubicin-loaded transferrin-modified nanoparticles sensitized glioma C6 cells to radiation, demonstrated by decreased colony formation." (PMID 32486019, 2020). "The TF regulatory network will lay the foundation for future research on the mechanism of action of LUZP2 in gliomas." (PMID 32695826, 2020). "The TfR is over-expressed in brain capillary endothelial and glioma cells 6 and its natural ligand is transferrin (Tf)." (PMID 32292496, 2020). "Similar observations were made when functionalized graphene oxide coated transferrin conjugated with FITC were incubated for 48 h in glioma U251 cells observed under fluorescent imaging." (PMID 32824281, 2020). "The results indicated that the approach of coadministering transferrin-based dual-targeting nanocarriers has excellent potential for anti-glioma drug delivery and tumor penetration." (PMID 30340364, 2018). "In gliomas, phase I and II clinical trials with the TfR ligand transferrin conjugated to diphtheria toxin have been conducted on patients with recurrent GBMs showing promising results." (PMID 28837569, 2017). "Nanoparticles that target glioma stem cell sub-populations, conjugate transferrin and encapsulate temozolomide, were developed as a potential therapeutic strategy to evaluate their effectiveness at damaging tumor cells." (PMID 29088799, 2017). "We investigated the relevance of the three-TF signature to regulation mechanisms of glioma carcinogenesis and suggested AHR, NFIL3 and ZNF423 as promising biomarkers for not only glioma molecular subtype diagnosis but also clinical treatment." (PMID 27586240, 2016). "In this study, to further intensify the targeting efficiency of LP, it was modified with RGD and TF to exert its superior glioma targeting property in vivo." (PMID 25289086, 2014). "In conclusion, the present study showed that 99mTc-TF uptake is higher than that of 99mTc-MIBI in all high-grade glioma cell lines studied." (PMID 25436147, 2014). "LPs exhibited higher toxicity following conjugation with RGD or TF, as the TF receptor and αvβ3 integrin are overexpressed in glioma cells." (PMID 25289086, 2014). "The targeting and penetration effects resulted in the highest glioma accumulation compared with single target RGD-LP or TF-LP, leading to the best imaging results." (PMID 25289086, 2014). "LPs modified with TF aided in the penetration and improved the glioma targeting, while RGD enhanced the cellular uptake and accumulation in the tumor." (PMID 25289086, 2014). "Aberrant TF expression has been detected in a variety of human tumors, including glioma, breast cancer, leukemia, colon cancer, pancreatic cancer, and non-small cell lung cancer, but is not found in corresponding normal tissues." (PMID 24086497, 2013). "When U373 glioma cells were evaluated using transferrin-Texas (TX) Red as a positive control, the inhibitory effect of chlorpromazine on the level of transferrin staining was observed as expected." (PMID 21838899, 2011). "Our results proved that Cur-Nio and TF-Cur-Nio not only exhibited excellent biocompatibility with normal cells but also demonstrated significant cytotoxicity and pro-apoptotic effects on C6 glioma cells." (PMID 40140588, 2025).
glioma (continued). "In summary, the pharmacodynamic evaluation of Cur-Nio and TF-Cur-Nio in an in-situ C6 glioma nude mouse model demonstrated that TF-Cur-Nio significantly outperformed both Cur-solution and Cur-Nio in terms of inhibiting glioma progression, inducing apoptosis, and extending survival." (PMID 40140588, 2025). "Moreover, glioma targeting with mNPs through transferrin functionalization has been nicely reported and analyzed previously." (PMID 38791253, 2024). "Basic experiments have shown that Sev can inhibit cell viability in a dose-dependent manner in U87 and U251 glioma cells, increase ROS levels and Fe2+ concentrations, upregulate the expression of transferrin, ferritin, and Beclin-1, and induce glial tumour cell death." (PMID 36313359, 2022). "A recent in vitro study combined the use of transferrin decorated magnetic nanoparticles with a different type of non-toxic quantum dots, namely ﻿InP/ZnS quantum dots, to investigate dual targeting and imaging of glioma." (PMID 35715639, 2022). "Moreover, ATF4 suppression obviously reversed the regulatory role of Sev on protein levels of GPX4, transferrin, and ferritin in glioma cells." (PMID 35372041, 2022). "It was previously reported that TF expression can be stimulated by EGF in glioma cells." (PMID 32923403, 2020). "As human gliomas represent another mTOR pathway-activated cancer type arising from its frequent occurrence of EGFRvIII and/or loss of tumor suppressor PTEN, we also examined TF expression in these tumors." (PMID 32923403, 2020). "A previous report showed that a transferrin-imaging agent is able to target gliomas selectively." (PMID 32112540, 2020). "In this study, the authors develop transferrin-functionalized nanoparticles able to traverse the intact blood-brain barrier and deliver combination temozolomide and bromodomain inhibitor therapy to glioma-bearing mice." (PMID 29777137, 2018). "In addition, transferrin nanoparticles encapsulating temozolomide have the potential of a promising anti-tumor strategy against glioma of the O6-methylguanine-DNA-methyltransferase gene promoter methylation." (PMID 29088799, 2017). "In addition, biotinylated PEG-PLA block copolymers obtained via ring opening polymerization were successfully functionalized with transferrin that showed better internalization in C6 glioma cells compared to unmodified one." (PMID 29464123, 2017). "99mTc-TF uptake was higher than 99mTc-MIBI in all studied high-grade glioma cell lines." (PMID 25436147, 2014). "Lastly, the group led by Miyata reported a 3.6-fold higher 10B tumor concentration in orthotopic gliomas after intratumoral convection-enhanced delivery using PEGylated transferrin armed liposomes over untargeted liposomes with a lower retention in normal brains." (PMID 23533772, 2013). "Decreased NF-κB activity—which is upregulated in glioma—induced by curcumin may result in decreased proliferation, cell survival, angiogenesis, inflammation, and increased apoptosis since this TF directly regulates the expression of genes involved in these processes." (PMID 38397870, 2024). "Additionally, PEG-PLA conjugated to transferrin (Tf) was used to target glioma." (PMID 33202681, 2020). "Transferrin (Tf)-modified (PAMAM) dendrimer which has great brain targeting efficiency was used to deliver (hTRAIL)-encoding plasmid in C6 cells and showed enhanced cytotoxicity, glioma targeting, and enhanced permeability and retention (EPR) effect in comparison to non modified NPs." (PMID 27594905, 2016). "RGD and TF could effectively increase the efficiency of LPs targeting to glioma." (PMID 25289086, 2014). "Thus, 99mTc-TF is anticipated to be a superior tracer to 99mTc-MIBI for gliomas imaging in vivo." (PMID 25436147, 2014).